FTO (FTO alpha-ketoglutarate dependent dioxygenase)
Diseases named in the same sentence as FTO in open-access papers (continued):
Sharing a sentence is not in itself a finding about the gene and the disease.
breast cancer (continued). "STAT3 also binds with FTO promoter to activate its transcription in breast cancer cells." (PMID 38297099, 2024). "Finally, we investigated the biological functions of the FTO/GAS5/IGF2BP2/QKI axis in breast cancer." (PMID 38782769, 2024). "FTO contributes to drug resistance in various cancers, including cervical cancer, gastric cancer, melanoma, breast cancer, leukemia, colorectal cancer, bladder cancer, and glioma." (PMID 39295930, 2024). "MO-I-500 also inhibits the survival and colony formation of breast cancer cells by inhibiting FTO." (PMID 38560499, 2024). "The role of FTO in breast cancer is complex and contradictory." (PMID 38545841, 2024). "Then, we examined the expression of FTO in breast cancer tissues and cells." (PMID 38782769, 2024). "Recent studies have demonstrated that FTO acts as an oncogene to promote the progression of various human cancers including breast cancer, suggesting that FTO may be a potential target for cancer therapy." (PMID 38782769, 2024). "Moreover, overexpression or knockdown of FTO affected the inhibitory effect of GAS5 on the proliferation of breast cancer cells." (PMID 38782769, 2024). "Thus, the inclusion of FTO and PIK3CB in the diagnostic panel can enhance the diagnostic effectiveness of CEA and CA15-3 in breast cancer." (PMID 37861518, 2023). "Combining FTO, PIK3CB, CEA and CA15-3 improves the diagnostic efficiency of breast cancer." (PMID 37861518, 2023). "Moreover, the combination of FTO, PIK3CB, CEA, and CA15-3 exhibited an improved diagnostic value for breast cancer compared to the use of CEA or CA15-3 alone." (PMID 37861518, 2023). "Furthermore some researchers believe that FTO primarily stimulates the oncogenic activity of breast cancer cell invasion and migration through the FTO/miR-181b-3p/ARL5B signaling pathway, promoting tumor proliferation." (PMID 35707365, 2022). "Furthermore, MO-I-500 was found to be a selective FTO inhibitor, which restrains the survival and colony formation of breast cancer cells." (PMID 36553003, 2022). "In breast cancer, the expression of FTO is up-regulated while that of BNIP3 is down-regulated." (PMID 35141221, 2022). "FTO is overexpressed in breast cancer cells, which affects the energy metabolism of the cells." (PMID 36344993, 2022). "In addition, ALKBH5, as the second m6A demethylated enzyme discovered after FTO, was reported to promote tumor stem formation in gliomas and promote tumor progression in breast cancer, colon cancer and hepatocellular carcinoma." (PMID 36347025, 2022). "The trend wherein knockdown of Fto resulted in increased apoptosis was also seen in breast cancer and melanoma, suggesting that FTO may also serve an oncogenic function in these cancers by inhibiting apoptosis." (PMID 35350378, 2022). "For example, FTO promoted breast cancer progression by increasing the RNA degradation of the pro-apoptosis gene BNIP3 via m6A demethylation and a YTHDF2-independent mechanism and promoted glioblastoma tumorigenesis and cancer stem cell self-renewal as a component of the m6A regulatory machinery." (PMID 34218271, 2021). "have proven that FTO could reduce apoptosis in breast cancer cells by inducing BNIP3 mRNA degradation." (PMID 34211849, 2021). "Researchers found that FTO could effectively promote cell proliferation, colony formation, and metastatic process in breast cancer." (PMID 34399770, 2021). "Recently, one study also illustrated that FTO expression may play an essential role in the development and aggressiveness of breast cancer, especially HER2-overexpressing breast cancer." (PMID 34044876, 2021). "Likewise, the knowledge of Rhein, the effective FTO inhibitor, competitively prevented the recognition of m6A modified substrate by FTO, which alleviated the growth of subcutaneous breast cancer in mice." (PMID 34211849, 2021). "FTO expression is increased in breast cancer and promotes cell growth and metastasis." (PMID 35087575, 2021).
breast cancer (continued). "In breast cancer, a YTHDF2-dependent mechanism underlies the degradation of the BCL2 interacting protein 3 (BNIP3) mRNA, which would otherwise encode an apoptosis-promoting protein that is a downstream target of FTO-mediated m6A modifications." (PMID 34105069, 2021). "One researcher showed that FTO expression is low in HER2-positive breast cancer." (PMID 34044876, 2021). "Recent studies found that the expression of FTO is upregulated in human breast cancer." (PMID 34211849, 2021). "FTO overexpression implies poor DFS/OS/RFS for HER2-positive breast cancer." (PMID 34044876, 2021). "Furthermore, FTO proves to promote glycolysis though PI3K/AKT pathway in breast cancer cells 29 and PI3K/AKT signaling pathway was also enriched in our DEGs." (PMID 34149936, 2021). "Variants of the FTO gene have been reported to be associated with endometrial, pancreatic and breast cancer risk but not to be associated with prostate cancer risk." (PMID 34345232, 2021). "In addition, the eraser FTO is up-regulated in breast cancer where it down-regulates the pro-apoptotic factor BNIP3 to mediate breast cancer proliferation, progression, and metastasis." (PMID 33376192, 2021). "Oestrogen may promote breast cancer cell proliferation through up‐regulation of FTO gene expression and activation of the PI3 K/Akt signalling pathway in oestrogen receptor‐positive patients." (PMID 33634577, 2021). "Recently, several selective inhibitors of FTO have been investigated, among which meclofenamic acid (MA) and MO-I-500 were found to effectively suppress glioblastoma progression and breast cancer cell survival by inhibiting the catalytic activity of FTO." (PMID 32443966, 2020). "In breast cancer, FTO enhances breast cancer cell growth, colony formation and metastasis." (PMID 33015074, 2020). "Next, we demonstrated that silence of FTO could significantly reduce breast cancer cell proliferation, colony formation and enhance cell apoptosis." (PMID 30922314, 2019). "Based on the data, we revealed the important role of m6A modification mediated by FTO in breast cancer, and proposed that FTO may act as a novel therapeutic target in breast cancer progression." (PMID 30922314, 2019). "In another study, the FTO rs11075995 variant risk allele was reported to be associated with breast cancer risk, without adjustment for body mass index (BMI)." (PMID 31447604, 2019). "Our findings demonstrate the functional significance of the m6A modification in breast cancer, and suggest that FTO may serve as a novel potential therapeutic target for breast cancer." (PMID 30922314, 2019). "To determine whether BNIP3 was the main downstream target of FTO to regulate breast cancer initiation and progression, we generated double knockdown (shBNIP3 and shFTO) breast cancer cell lines." (PMID 30922314, 2019). "Our findings have revealed a role of FTO in regulation of apoptosis and growth of breast cancer, and theoretically, it suggests that FTO may be a potential therapeutic target for breast cancer." (PMID 30922314, 2019). "Moreover, we also detected that BNIP3 was upregulated in FTO inhibiting or FTO silencing tumor samples in 4T1-hypodermic breast cancer models." (PMID 30922314, 2019). "We showed that FTO, a key m6A demethylase, was up-regulated in human breast cancer." (PMID 30922314, 2019). "Altogether, our findings suggest that FTO may serve as a novel potential therapeutic target for breast cancer." (PMID 30922314, 2019). "To determine whether FTO was critical to breast cancer cell growth, we generated two stable FTO-knockdown models in human MDA-MB-231 and MCF-7 cell lines, by infecting two distinct shRNA lentivirus (shFTO#1 and shFTO#2)." (PMID 30922314, 2019). "We further confirmed the up-regulation of FTO in the group of DNBC (ER−/PR−/Her2+) and late stages (GRADE II and III) three clinical stages of breast cancer, suggesting that FTO may play a predominant role in mediating m6A modification in breast cancer." (PMID 30922314, 2019).
breast cancer (continued). "FTO rs11075995 SNP risk allele was associated with breast cancer risk without adjustment for BMI (OR=1.08, 95%CI=1.01-1.15)." (PMID 28881622, 2017). "Overall, our results suggest that genetic variations in FTO gene may play roles in breast cancer pathogenesis in women." (PMID 26146447, 2015). "Our findings point toward an important role of FTO in breast cancer." (PMID 21489227, 2011). "However, research has also shown that inhibiting FTO activity may actually promote the proliferation and invasion of breast cancer cells, an effect that aligns with the induction of epithelial-mesenchymal transition (EMT)." (PMID 40016470, 2025). "In this context, FTO inhibition could be a potential therapeutic strategy for breast cancer." (PMID 38545841, 2024). "Therefore, we assessed the diagnostic value of fat mass and obesity-associated protein (FTO), phosphatidylinositol-4,5-biphosphate 3-kinase catalytic subunit β (PIK3CB) as a potential complementary biomarker to CEA and CA153 in breast cancer by measuring serum FTO,PIK3CB levels." (PMID 37861518, 2023). "Additionally, FTO was found to be upregulated in breast cancer tissues." (PMID 32398132, 2020). "Interestingly, it has been demonstrated that m6A “eraser” FTO was significantly up-regulated in breast cancer, which could promote breast cancer cell proliferation, colony formation and reduce apoptosis." (PMID 33363011, 2020). "FTO might be regarded as a novel target for breast cancer therapy." (PMID 32226518, 2020). "Moreover, with clinical outcome analysis, we found that up-regulation of FTO was significantly associated with lower survival rates in patients with advanced stage of breast cancer and patients with ER negative breast cancer." (PMID 30922314, 2019). "Nonetheless, we found all the alleviations were limited that could not recur in the control group, which indicating that the FTO-m6A-BNIP3 signaling pathway may partially explain the effects on breast cancer initiation and progression caused by FTO." (PMID 30922314, 2019). "Similarly, depleting FTO inhibited breast cancer cell colony-forming abilities." (PMID 30922314, 2019). "However, the adjustment to BMI led to the disappearance of this association, indicating that there is no independent association between the FTO polymorphism and the risk of breast cancer." (PMID 31447604, 2019). "Indeed, several recent studies have suggested that FTO plays an oncogenic role in various types of cancers such as leukemia, brain tumor, breast cancer, gastric cancer, endometrial carcinoma, and cervical squamous cell carcinoma (CSCC) where it is overexpressed." (PMID 30105001, 2018). "Our updated meta-analysis shows that FTO rs9939609 SNP was associated with some types of cancer, such as endometrial cancer, pancreatic cancer and breast cancer without adjustment for BMI, while it was still associated with breast cancer and prostate cancer with adjustment for BMI." (PMID 28881622, 2017). "However, FTO rs11075995 variant risk allele was associated with breast cancer risk without adjustment for body mass index, but the association disappeared with further adjustment for body mass index." (PMID 28881622, 2017). "Besides, the association of FTO SNPs with survival of breast cancer has not been studied in Chinese population." (PMID 26146447, 2015). "In sum, FTO and BTK are important regulators of c-Myc and E2F1 accumulation in breast cancer, and their induction of low expression levels is a major factor in improving the survival outcomes of breast cancer patients." (PMID 41281757, 2025). "Collectively, the combined inhibition of FTO and BTK exhibited substantial synergistic anticancer effects in breast cancer." (PMID 41281757, 2025). "Significantly, our study revealed that MIDN was highly expressed in gastric and breast cancers, and the knockdown of MIDN upregulated FTO protein levels both in SNU-216 and MCF-7 cells." (PMID 40002690, 2025).
breast cancer (continued). "The FB23-everolimus combination synergistically inhibits pancreatic neuroendocrine tumors 15; similarly, the combination of FB23 and BX-912 targets FTO and the PDK1-AKT pathway to suppress breast cancer." (PMID 41281757, 2025). "Since we showed earlier that LIP stimulates the migration of breast cancer as well as untransformed breast epithelial cells, we investigated whether overexpression of C/EBPβ‐LIP would reverse the reduced MDA‐MB‐231 cell migration phenotype caused by FTO knockdown." (PMID 40022434, 2025). "Mostly, FTO was found to act as an oncogene, for example in acute myeloid leukemia (AML) subtypes, breast cancer and glioma." (PMID 40022434, 2025). "Similarly, in breast cancer (BC), the inhibition of 5′-tRF-GlyGCC binding to FTO can promote autophagy, which increases the m6A level of eIF4G1 in BC cells and inhibits growth and metastasis." (PMID 39468015, 2024). "In pulmonary metastases of breast cancer cells, it was found that METTL3 expression is increased while FTO expression is decreased." (PMID 39192357, 2024). "GAS5 suppressed breast cancer growth via IGF2BP2/QKI, and this inhibitory effect was modulated by FTO both in vitro and in vivo." (PMID 38782769, 2024). "Previous reports showed that the upregulation of FTO enhanced cell migration and invasion by affecting the miR-181b-3p (microRNAs, miRNAs)/ARL5B signaling pathway in breast cancer." (PMID 38782769, 2024). "In conclusion, YTHDF2 and FTO increase the stability and expression of ZEB1 mRNA, leading to drug resistance and high aggressiveness of breast cancer cells." (PMID 38031146, 2023). "In breast cancer, senile neutrophils produce exosome piR-17,560 in a STAT3-dependent manner, which binds to FTO and increases ZEB1 expression by reducing m6A methylation, promoting chemotherapy resistance and EMT in BC cells." (PMID 38031146, 2023). "FTO demethylates m6A in the 3′-UTR of BNIP3 and reduces its expression; this promotes the proliferation, colony formation, and metastasis of breast cancer cells." (PMID 35141221, 2022). "FTO has also been investigated in tumorigenesis, where emerging studies suggest m6A and FTO levels are dysregulated in various cancers, including acute myeloid leukemia (AML), glioblastoma, cervical squamous cell carcinoma (CSCC), breast cancer, and melanoma." (PMID 35409166, 2022). "On the other hand, the m6A eraser, FTO was found to promote the degradation of BNIP3 and inhibited the proliferation and invasion of breast cancer cells." (PMID 35646049, 2022). "Recent advances have highlighted that FTO and ALKBH5 play an oncogenic role in various cancers, such as acute myeloid leukemias (AML), glioblastoma, and breast cancer." (PMID 35628623, 2022). "FTO also promotes EMT and breast cancer lung metastasis by regulating the translational extension of KRT7 mRNA via YTHDF1/eEF-1." (PMID 36358640, 2022). "More importantly, there is growing evidence that FTO dysfunction can promote the development of cancers, such as acute myeloid leukemia (AML), melanoma, breast cancer, and lung cancer." (PMID 35064107, 2022). "With compared the expression of ALKBH family members in breast cancer and normal samples, the up-regulation was ALKBH1, ALKBH2, ALKBH4, ALKBH6, ALKBH7, and others such as ALKBH3, ALKBH8, FTO was down-regulation." (PMID 35980268, 2022). "FTO mediates m6A demethylation in the 3’UTR of BNIP3 mRNA and induces its degradation through a YTHDF2-independent mechanism, promoting breast cancer cell proliferation, colony formation, and in vitro and in vivo transfer." (PMID 35707365, 2022). "In the breast cancer TCGA datasets, we found that the expression of ZEB1 was positively correlated with FTO." (PMID 36302751, 2022). "In breast cancer, eight genes (METTL3, KIAA1429, ZC3H13, FTO, YTHDF1, YTHDF2, IGF2BP2, and IGF2BP3) were significantly enriched in tumor cells compared to immune or stromal cells." (PMID 35794212, 2022).
breast cancer (continued). "Hence, we propose that FTO may be an effective target for the treatment of breast cancer." (PMID 35628623, 2022). "FTO can also target and remove the m6A modification of the 3-‘UTR of BNIP3, resulting in degradation of BNIP3 and subsequent proliferation of the breast cancer cells." (PMID 33926508, 2021). "For example, in colorectal carcinoma, SOX2 promotes cancer through methylation catalyzed by METTL3, while in breast cancer, BNIP3 promotes the cancer through demethylation catalyzed by FTO." (PMID 34489709, 2021). "For instance, FTO can not only accelerate the progression of AML and breast cancer, but also be treated as an anti-oncogene in ICC." (PMID 34211849, 2021). "Among them, the expression of RBM15, VIRMA, HNRNPA2B1, and YTHDF1/2/3 were significantly upregulated, but METTL3, METTL14, METTL16, WTAP, FTO, YTHDC1, and EIF3A had lower expression in breast cancer compared to normal samples." (PMID 34804948, 2021). "As an m6A eraser, FTO demethylates the 3′ UTR of the BNIP3 mRNA and induces its decay in an YTHDF2-independent manner, resulting in breast cancer cell proliferation, colony formation, and metastasis." (PMID 33292526, 2020). "For example, in CRC, SOX2 plays a cancer-promoting role through METTL3-catalyzed methylation, while in breast cancer, BNIP3 plays a cancer-promoting role through FTO-catalyzed demethylation." (PMID 32398132, 2020). "In this study, by analyzing the prognostic role of m6A modulators (METTL3, METTL14, WTAP, FTO, and ALKBH5) in breast cancer using on-line databases, we found that only METTL3 played an important role in TNBC metastasis." (PMID 32766145, 2020). "Niu et al20 found that the m6A demethylase fat mass and obesity‐associated protein (FTO) promoted proliferation, colony formation and metastasis of human breast cancer cells; BNIP3 is a downstream target of FTO‐mediated m6A modification." (PMID 33098220, 2020). "To further verify the oncogenic role of FTO in breast cancer, we performed a subcutaneous implantation experiment in BALB/c mice to examine the effect of FTO-knockdown in breast cancer tumorigenicity." (PMID 30922314, 2019). "As a functional target of FTO, BNIP3 is required for cell apoptosis, suggesting its role as tumor suppressor in breast cancer." (PMID 30922314, 2019). "While we shed light on the epigenetic regulation by FTO in breast cancer, ALKBH5, another m6A demethylase, was previously reported to affect breast cancer stemness phenotype in hypoxia." (PMID 30922314, 2019). "To verify BNIP3 as a FTO downstream target, we detected both BNIP3 mRNA expression level and protein expression level in breast cancer cells." (PMID 30922314, 2019). "FTO mRNA levels were modestly increased (1.4 fold) in ZR-75.1 cells, decreased in SUM-159 cells, and unchanged in other breast cancer lines under hypoxic conditions." (PMID 27590511, 2016). "In line with this, we investigated whether FTO and BTK influence OS in breast cancer patients through c-Myc and E2F1." (PMID 41281757, 2025). "In breast cancer (BRCA), the model selected HNRNPC, IGF2BP2, IGF2BP3, FTO, METTL16, and ALKBH1." (PMID 40565233, 2025). "Similarly, overexpression of the demethylase FTO promotes the progression of breast and colon cancers, whereas FTO deletion induces EMT and promotes breast cancer metastasis." (PMID 41285728, 2025). "Inhibitors targeting FTO or STAT3 can reduce doxorubicin resistance, which may be a potential therapeutic strategy for breast cancer." (PMID 40483535, 2025). "Moreover, FTO promotes the doxorubicin resistance driven by signal transducer and activator of transcription 3 (STAT3) in breast cancer." (PMID 40483535, 2025). "FTO inhibitors can suppress the proliferation and metastasis of breast cancer, while its efficacy is not satisfactory and needs to be further improved." (PMID 41281757, 2025).